BRCA2 (BRCA2 DNA repair associated)
Diseases named in the same sentence as BRCA2 in open-access papers (continued):
Sharing a sentence is not in itself a finding about the gene and the disease.
colorectal cancer (103 papers, 2001 to 2025). A primary or metastatic malignant neoplasm that affects the colon or rectum. "The only significant association unrelated to BRCA2 was between colorectal cancer and SH2B3 in EUR-like individuals (p = 1.2 × 10−4, OR = 5.3)." (PMID 39799398, 2025). "Between the two commonly known BRCA genes, BRCA2 harbors a greater risk of gastrointestinal cancers, in particular colorectal cancers." (PMID 39421182, 2024). "Unadjusted odds ratios (ORs) were used to estimate the probability of Breast Cancer Type 1 Susceptibility gene (BRCA1) and Breast Cancer Type 2 Susceptibility gene (BRCA2) mutations in colorectal cancer patients." (PMID 37644384, 2023). "A significant increase in the frequency of BRCA1 and BRCA2 mutations was observed in patients with colorectal cancer [OR = 1.34, 95% confidence interval (CI) = 1.02–1.76, P = 0.04]." (PMID 37644384, 2023). "Further studies should focus on the situation of male BRCA1 or BRCA2 mutation carriers or on the situation of mutation carriers in other hereditary diseases (e.g. familial colorectal cancer)." (PMID 34635688, 2021). "Since olaparib is known to induce synthetic lethality in BRCA-mutated tumors, we selected the BRCA2-deficient colorectal cancer cell line (DLD-1 BRCA2 -/-) for this study." (PMID 31618864, 2019). "This study aimed to investigate whether BRCA1 and BRCA2 gene mutations are associated with colorectal cancer risk." (PMID 37644384, 2023). "Indeed, biallelic BRCA2 mutations have been observed in a 31 years old female diagnosed with colorectal cancer." (PMID 34456966, 2021). "Furthermore, any breast-colorectal GWAS signal was less likely to be due to syndromic cases since all cases carrying BRCA1 or BRCA2 or known colorectal cancer susceptibility gene mutations were excluded from the GWAS." (PMID 29698419, 2018). "Among individuals with mutations in CHEK2, BRCA2, PMS2, and APC, a high proportion reported a family history of breast, ovarian, prostate, pancreatic, or colorectal cancer (8 out of 11 considered patients)." (PMID 41294693, 2025). "This expansion of PARP inhibitor use is compelling given the partial response observed in a colorectal cancer patient with a germline BRCA2 p.K944*." (PMID 39085400, 2024). "In subgroup analysis, colorectal cancer patients had an increased odds of BRCA1 (OR = 1.48, 95% CI = 1.10–2.01, P = 0.01) and BRCA2 (OR = 1.56, 95% CI = 1.06–2.30, P = 0.02) mutations." (PMID 37644384, 2023). "We report that histone acetyltransferase KAT2B decreases BRCA2 expression by reducing the acetylation of the 27th amino acid in histone H3 (H3K27) at the promoter of the BRCA2 gene in colorectal cancer (CRC)." (PMID 38067284, 2023). "For BRCA2, there was an increase of carriers with an additional uterine (8.47%), lung (6.78%), or colorectal cancer (6.78%)." (PMID 36199081, 2022). "In this analysis, the top three most common genes with founder mutations were PRKDC (n = 31 colorectal cancer samples from the TCGA dataset), ATM (n = 18 samples), and BRCA2 (n = 17 samples)." (PMID 35054819, 2022). "The occurrence of first colorectal cancer followed by second colorectal cancer have been commonly identified with BRCA1/BRCA2, and MMR genes." (PMID 34556087, 2021).
colorectal cancer (continued). "BRCA2−/− colorectal cancer cells DLD1 co-treated with olaparib and NSC617145 also displayed a greater reduction in proliferation than that due to an additive effect of the two drugs acting independently." (PMID 34772932, 2021). "The biallelic BRCA2 genotype has also been observed in a 31-year-old female diagnosed with colorectal cancer." (PMID 34456966, 2021). "The spectrum of cancers affecting carriers of c.9334G>A variant is wide- with the exception of leukemia, thyroid and colorectal cancer all other malignancies are part of the BRCA2 phenotype." (PMID 30286154, 2018). "PCAT1 and CCAT1 have been identified as prognostic markers in prostate and colorectal cancers acting as transcriptional regulators of the genes BRCA2 and MYC respectively." (PMID 28945760, 2017). "And indeed, our results show that colorectal cancers express higher levels of Rad51 and BRCA2 than normal mucosa." (PMID 25909291, 2015). "Additionally, mutations in BRCA2 and CDKN2A have been associated with the pathogenesis of colorectal cancer." (PMID 40447784, 2025). "In a systematic review of 18 studies and a meta-analysis of 14 studies, the risk of colorectal cancer was shown to be moderately elevated in BRCA1 (a 1.49-fold higher risk of CRC in BRCA1 mutation carriers) but not in BRCA2 mutation carriers." (PMID 37761360, 2023). "Similarly, the co-existence of the BRCA2 and PMS2 mutations prompted the development of breast and colorectal cancer in the same patient." (PMID 36232793, 2022). "Furthermore, we investigated the in vivo response to pyridostatin using a second tumour model, established from isogenic BRCA2+/+ and BRCA2−/− colorectal carcinoma HCT116 cells." (PMID 35107878, 2022). "The two allelic variants of BRCA2 were found in blood, skin tissue, and in three primary tumor samples: invasive ductal carcinoma (IDC), contralateral ductal carcinoma in situ (DCIS), and colorectal cancer (CRC) identified during a necropsy study." (PMID 34504103, 2021). "However, a recent meta-analysis concluded that BRCA1 and/or BRCA2 mutation carriers are not at a higher risk of colorectal cancer." (PMID 37296477, 2023). "Colorectal cancer risk increases in BRCA1 but not in BRCA2 mutation." (PMID 32349445, 2020). "We show that breast cancer gene 2 (BRCA2) is highly expressed in cultured olaparib-resistant colorectal cancer (CRC) cells and that CRC cells become more sensitive to olaparib with reduced BRCA2 expression." (PMID 38067284, 2023). "To support the role of BRCA2 expression for olaparib sensitivity in colorectal cancer, we first detected the IC50 of olaparib in three different colorectal cancer cell lines: HCT116, HCT15, and SW480." (PMID 38067284, 2023). "To confirm these findings, we generated an additional ATM KO in the colorectal carcinoma cell line DLD1, for which a BRCA2 KO was already available." (PMID 36969741, 2022). "As such, the human colorectal cancer isogenic cell line pair DLD-1 parental and DLD-1 BRCA2 -/-, the latter harboring a defect in the DNA double strand repair gene, was used." (PMID 31618864, 2019).
colorectal cancer (continued). "In colorectal cancer, the genes that were significantly enriched for copy number gain in TCGA versus GENIE were BRCA2 (60% versus 23%, p < 0.0001), BRAF (48% versus 11%, p < 0.0001) and KRAS (22% versus 3%, p < 0.0001)." (PMID 30728399, 2019). "Drug efficacy was thus evaluated in short-term (3 days) or long-term (12 days) cultures of cancer cell lines, including a colorectal cancer cell line with (DLD1-KO) or without BRCA2 knockout (DLD1-P)." (PMID 38789724, 2024). "Differences in cancer risks between male relatives of BRCA2 carriers and non-carriers, however, were not significant with respect to gastric, liver, and colorectal cancers." (PMID 36861435, 2023). "In this meta-analysis, we were surprised to find a potential protective effect of BRCA gene mutations against colorectal cancer in three studies that did not distinguish between BRCA1 and BRCA2." (PMID 37644384, 2023). "In both breast and colorectal cancer, CD44 and BRCA2 showed a strong positive correlation." (PMID 32610620, 2020). "However, a limitation of this case report is the absence of HRD testing to assess the involvement of BRCA2 in the development and progression of colorectal cancer." (PMID 39985003, 2025). "Second, it is possible that we missed pathogenic germline variants in moderate penetrance colorectal cancer genes such as ATM, SMAD3, or high penetrance syndromes primarily associated with other cancers such as BRCA1 and BRCA2, which were not part of our panel." (PMID 31647837, 2019). "The strength of the family history of colorectal cancer would not, however, be in keeping with the slight increases in colorectal risk seen with BRCA mutations; these are usually seen in those with BRCA1 mutations rather than BRCA2." (PMID 19493351, 2009). "However, whether BRCA2 mutations increase the risk of colorectal cancer remains controversial; some studies suggest that BRCA1 pathogenic variants may be associated with colorectal cancer risk, while BRCA2 variants are not." (PMID 39985003, 2025). "Differences in the risks for other cancers (liver, gastric, and colorectal cancers) between female relatives of BRCA1 and BRCA2 carriers were not significant." (PMID 36861435, 2023).
hereditary cancer (88 papers, 2005 to 2026). Malignant neoplasms occurring in families at a rate greater than that expected by chance and caused by germline mutations in a specific gene. "Mutations in the BRCA1 and BRCA2 genes significantly increase the risk of hereditary cancers, mainly of the breast and ovary, but also of other cancers such as those of the pancreas, prostate and cervix." (PMID 40949480, 2025). "Some hereditary cancer genes (e.g. BRCA2, FANCM, MLH1, WT1) have been directly linked to human infertility." (PMID 40060932, 2025). "Mutations in the BRCA2 gene are associated with sporadic and familial cancer, cause genomic instability and sensitize cancer cells to inhibition by the poly(ADP-ribose) polymerase (PARP)." (PMID 37488236, 2024). "Pathogenic variations in the BRCA2 gene have been detected with the development of next-generation sequencing (NGS)-based hereditary cancer panel testing technology." (PMID 38927659, 2024). "A 47-gene panel of common hereditary cancers was performed, and 2 pathogenic variants were identified in the BRCA2 and BRIP1 genes." (PMID 38912178, 2024). "BRCA2 is prototypical tumor suppressor gene involved in DNA repair (through homologous recombination) and in familial cancer susceptibility." (PMID 39138582, 2024). "Machine learning-based pathogenicity prediction helps interpret rare missense variants of BRCA1 and BRCA2, which are associated with hereditary cancers." (PMID 37380723, 2023). "Second, the study did not have access to personal history, family history, and status of genetic mutations, such as those in BRCA1/BRCA2, which influence hereditary cancer." (PMID 37781206, 2023). "We compared our results with the BRCA1 and BRCA2 mutational spectrum reported by the Brazilian Consortium of Hereditary Cancer, as well as other studies." (PMID 35353237, 2022). "Our patient knew about the risk of BRCA2 and hereditary cancer risk and since he had 50% BRCA2 allele frequency, he consented for genetics counseling which confirmed germline BRCA2 mutations." (PMID 34161676, 2021). "Conventional methods used to identify BRCA1 and BRCA2 germline mutations in hereditary cancers, such as Sanger sequencing/multiplex ligation-dependent probe amplification (MLPA), are time-consuming and expensive, due to the large size of the genes." (PMID 31065452, 2019). "The mutation spectrum of BRCA1 and BRCA2 mutations in the largest hereditary cancer clinic in Norway is diverse." (PMID 29339979, 2018). "Because of the potential to miss such mutations, re-testing of individuals who previously had limited BRCA1 and BRCA2 testing should be considered, particularly in ethnicities with elevated risk or if a strong suspicion for hereditary cancer otherwise remains." (PMID 28281021, 2017). "We identified deleterious heterozygous germline mutations in well-established familial cancer-associated genes, BRCA2, PALB2, ATM and MLH1, in 14.5% (8/54) of our FPC patients." (PMID 27732944, 2016). "Mutations of the BRCA1 and BRCA2 genes, encoding two proteins involved in DNA repair, underlie most cases of such hereditary cancers." (PMID 23354980, 2013). "A Delphi survey of 16 expert genetics and cancer health professionals and 16 service users with cancer and a BRCA1/BRCA2 pathogenic variant agreed that information about inheritance, genetic testing, cancer risks and the management of hereditary cancer were key messages for cancer patients." (PMID 30573802, 2019). "De novo FAP with double germline mutations in APC and BRCA2, along with somatic ERBB2 mutations, is exceptionally rare among hereditary cancer cases." (PMID 39985003, 2025). "Variants in the hereditary cancer-associated BRCA1 and BRCA2 genes can alter RNA splicing, producing transcripts that encode internally truncated yet potentially functional proteins." (PMID 39741007, 2025).
hereditary cancer (continued). "The finding of low BRCAness measured by HRDetect among non-BRCA1/BRCA2 familial cancer indicates a low false positive rate for the classification of VUS in this clinically relevant patient group." (PMID 37316882, 2023). "Skaro et al27 reported that deleterious germline variations of hereditary cancer genes (eg, ATM, BRCA2, PALB2) were found in patients with IPMN associated with concurrent invasive cancer." (PMID 35171259, 2022). "It is also interesting to highlight candidate genes involved in hereditary cancer (BRCA2, BLM, ERCC2, SMARCA4) or connected to inherited CRC, such as Cowden syndrome (SEC23B) and Peutz–Jeghers syndrome (STK11IP)." (PMID 30871259, 2019). "The prevalence of hereditary cancers attributed to pathogenic variants in the BRCA1 and BRCA2 genes in unselected BC patients from Latin America and the Caribbean varies from 1.2% in Columbia to 27.1% in the Bahamas." (PMID 30400234, 2018). "Four variants classified as KP or EP in the BRCA2, PMS2, and SDHB genes have been recognized to cause different types of hereditary cancer." (PMID 30217213, 2018). "As a result of the increased availability to genetic testing for hereditary cancers, and improved models for functional assessment, the proportion of unclassified variants in BRCA1/BRCA2 has been progressively decreasing over time." (PMID 30400234, 2018). "POFT cancers have shared genetic backgrounds as parts of hereditary cancers related to BRCA1 and BRCA2 mutations and Lynch syndrome." (PMID 30089478, 2018). "POFT cancers are well established hereditary cancers based on mutations in BRCA1, BRCA2, and mismatch repair genes." (PMID 30089478, 2018). "Hereditary cancer panels have been constructed incorporating genes underlying well characterized cancer syndromes, such as BRCA1 and BRCA2, along with more recently discovered genes associated with increased cancer risk." (PMID 25886519, 2015). "Screening for the mutations carried out in several groups suggested significant variation of the relative contribution of BRCA1 and BRCA2 genes to hereditary cancer among the populations." (PMID 24711893, 2014). "Understanding tissue specific differences in DNA repair pathways can shed light on the tissue specificity of familial cancer-predisposing mutations in genes such as BRCA1, BRCA2, or APC." (PMID 25033455, 2014). "Earlier that month, another contributor to hereditary cancer had been unmasked when a putative BRCA2 gene was tentatively located on chromosome 13, by Michael Stratton and his team of UK scientists." (PMID 23369278, 2013). "Analysis of hereditary cancer cases (732 BC patients, 189 CRC patients, and 490 cancer-free elderly controls) revealed that 1% presented concurrent germline pathogenic variants in BRCA1, BRCA2, MUTYH, ATM, CHECK2, NBN, and RAD50." (PMID 37628631, 2023). "For example, Brca1 and Brca2 are tolerant of variation, ranking among the 9% ad 8% least constrained mouse genes; however, their human orthologues BRCA1 and BRCA2 contain high numbers of pathogenic variants that are causally linked to adult-onset hereditary cancer." (PMID 37736706, 2023).
hereditary cancer (continued). "Thus, strategies designed to induce the expression of in-frame transcripts that lack non-essential exons have the potential to rescue BRCA2 function in mutant cells, setting the basis for preventive interventions in individuals at high risk for hereditary cancer." (PMID 39741007, 2025). "Although the BRCA1 (NM_007294.3) and BRCA2 (NM_000059.3) gene variants were the primary focus of such studies in the past, hereditary cancer panel testing has recently replaced the approach involving only the BRCA1 and BRCA2 genes." (PMID 33558524, 2021). "Notably, 19% of BRCA1 or BRCA2 mutation carriers identified did not have a family history suggestive of hereditary breast and ovarian cancer syndrome and thus would not have been referred for, nor qualified for hereditary cancer testing." (PMID 29506471, 2018). "The field of hereditary cancer has changed significantly since the discovery of the BRCA1 and BRCA2 genes in the mid-1990s, and it is important that models of genetic service delivery evolve as well." (PMID 30428547, 2018). "The possible involvement of genes like BRCA1, BRCA2, CHEK2, and POT1, which are known to play a role in other hereditary cancers, could lead to new knowledge of UM, especially in family cases." (PMID 39926282, 2025). "In our analysis one of the BRCA1, BRCA2, RAD51C, and PALB2 mutations was found in 25.8% of familial cancer cases and in 9.9% of non-familial cases, similar to what has been reported previously." (PMID 33670479, 2021). "Although hereditary cancer was plausible, no samples were available from the three family members to investigate the presence of the BRCA2 VUS p.S1946P." (PMID 27907908, 2016).